CECR9 (cat eye syndrome chromosome region, candidate 9)
Gene: Gene on chromosome 22 (17,329,034 to 17,329,232, forward strand). Ensembl gene ENSG00000231004.
Subcellular location: Secreted